HMGA2 (high mobility group AT-hook 2)
Diseases named in the same sentence as HMGA2 in open-access papers (continued):
Sharing a sentence is not in itself a finding about the gene and the disease.
tumor (continued). "Let-7 employs its antiproliferative activities and its tumor-suppressor role by controlling key checkpoints of several mitogenic pathways and by suppressing different oncogenes, including HMGA2, RAS, and MYC." (PMID 34442460, 2021). "TRIM71 is also reported to act as a tumor suppressor due to its involvement in the post-transcriptional modulation of Lin28B-let-7-HMGA2 (high-mobility group AT-hook 2) signaling in tumorigenesis." (PMID 33923045, 2021). "Let 7 (Lethal-7) a tumor suppressor miRNA is downregulated in many malignancies with a resultant unchecked expression of HMGA2 and hence tumor progression." (PMID 33639654, 2021). "Next, we assessed the expression of HMGA2, a transcriptional marker for basal-like tumor cells in human PDAC, that is also expressed in murine KPC tumors and for which staining of murine tissue has been established previously." (PMID 34798385, 2021). "Among the genes consistently altered in HT29, HCT116, and SW620 cells, 13 genes had previously been reported associated with tumor metastasis, such as BTG2, MXD1, CDKN1A, and HMGA2." (PMID 33791222, 2021). "The levels of ZFAS1, miR-497-5p and HMGA2 in the excised tumour sections were measured after 35 days." (PMID 34552050, 2021). "Numerous tumor-related genes, such as HMGA2, RB1CC1/FIP200, SRCIN1, STAT3, and PTEN, are targeted by miR-20a." (PMID 33504017, 2021). "A de-repression of oncogenic let-7 targets, including K-Ras, c-Myc, and the DNA binding protein HMGA2, is part of the tumor-promoting activity of LIN28." (PMID 34298978, 2021). "Accumulated evidence indicated that high-expressed HMGA2 is predictive of tumor progression, poor prognosis and adverse side effects of treatment." (PMID 33536018, 2021). "There is increasing evidence linking HMGA2 to tumor initiation, development and metastasis, and this protein was shown to promote cancer development in the breast, colon, lung and ovary." (PMID 34680349, 2021). "Further mechanism studies showed that knockdown of RhoC downregulated HMGA2 expression, and HMGA2 expression was highly correlated with RhoC expression in OSCC tumor tissues via the analysis of TCGA datasets." (PMID 33519932, 2021). "HMGA2 was overexpressed in OSCC tumor tissues and further there was a close correlation between the expressions of RhoC and HMGA2 (P < 0.01, R = 0.39)." (PMID 33519932, 2021). "LINC01121, a newly identified tumor-related factor, was reported to be highly expressed in both BC specimens and the cell lines and exhibit a tumor-promotive role by promoting BC cell proliferation and invasion via regulating miRNA-150-5p/HMGA2." (PMID 39290802, 2021). "HMGA2 regulates gene expression by binding to AT-rich regions of DNA and thereby promotes tumor progression via different mechanisms." (PMID 34298978, 2021). "During EMT, HMGA2 promotes the binding of the de novo DNA methyltransferase 3A (DNMT3A) to the Cdh1 promoter, inducing the hypermethylation and silencing of the tumor-suppressor E-Cadherin (CDH1); this causes tumor cell invasion." (PMID 34439740, 2021). "On the basis of these results, we chose HMGA2, a potential tumor promoter and target of miR-490-3p in GC, for further studies." (PMID 33731207, 2021). "It has been shown that let-7 acts as a tumor suppressor by targeting pluripotency factors, including HMGA2." (PMID 34572843, 2021). "Studies have found that there is a negative correlation between the expression of high mobility group protein A2 (HMGA2) and miR-204-5p, and the expression of HMGA2 affects tumor volume and tumor progression stage." (PMID 34730054, 2021). "In accordance, HMGA2 expression showed a positive correlation with tumor grade and progression: expression of HMGA2 increases upon dedifferentiation tumors and with the presence of lymph node metastases." (PMID 34302528, 2021). "For example, we noted that cluster 5 cells express high levels of the embryonic marker Hmga2, a previously characterized marker of high-grade tumor cells." (PMID 33821796, 2021).
tumor (continued). "For example, lncRNA HOTAIR is positively correlated with metastasis of BC; HOTAIR acts as a sponge for miR-20a-5p and significantly influences the migration and invasion of tumor cells via the HOTAIR/miR-20a-5p/HMGA2 pathway." (PMID 34079084, 2021). "One of the known mechanisms underlying the pro-tumoral functions of HMGA2 is its role in the induction of epithelial–mesenchymal transition (EMT), a process linked to the acquisition of metastatic capability of tumor cells." (PMID 34302528, 2021). "Compared with the siNC group, siLINC009636 significantly inhibited the expression of miR-532-3p and promoted HMGA2 expression in the tumor." (PMID 33536018, 2021). "In epithelial carcinoma, HMGA2 promotes tumour growth and metastasis through activation of the ERK signalling pathway and EMT phenotype, respectively." (PMID 34539580, 2021). "In this literature review, we highlight the oncogenic role of HMGA2 in tumor development and progression and discuss the probable signaling pathways affected by this architectural protein." (PMID 33668453, 2021). "The important roles of HMGA2 and its downstream genes in tumor progression have been demonstrated in earlier studies." (PMID 32719345, 2020). "The chromatin remodeling protein HMGA2 was reported to be upregulated in hybrid E/M and mesenchymal state tumor cells of the mouse prostate, as well as in human CRPC." (PMID 33297508, 2020). "The important roles of HMGA2 and its downstream genes in tumor progression have been demonstrated in previous studies." (PMID 32719345, 2020). "The response to WNT10B is abolished by interfering with HMGA2 function in Wnt10b-driven tumor cells." (PMID 31963852, 2020). "This decrease led to inhibited expression of SOX2, which is a target gene of HMGA2 and a master regulator of stemness features, thus inducing the suppression of cancer cell pluripotency and tumour cell growth." (PMID 31979076, 2020). "Our previous study suggested miR-370–3p functions as a tumor suppressor gene by targeting HMGA2 in NF-PitNET and the tumor suppressor effect was regulated by SDF-1α." (PMID 33362712, 2020). "Seven weeks after transplantation, the average tumor volume was 970.2 ± 476.9 mm3 for HMGA2-overexpressing C2C12 cells but 27.2 ± 28.4 mm3 for control C2C12 cells (P < 0.01)." (PMID 32489328, 2020). "Of the tumours employed for long term culture, relative quantification of HMGA2 mRNA in original tumour samples demonstrated upregulation in two tumours (L5, L10) compared to matched myometrium, while tumour L8 showed increased levels in myometrium." (PMID 32251338, 2020). "Full length HMGA2 transcripts can form in these tumor types when chromosomal rearrangements occur in an extragenic location usually upstream of the HMGA2 coding region." (PMID 32365712, 2020). "VB treatment or let‐7g‐5p overexpression inhibited HMGA2 expression and the activation of Wnt/β‐catenin signalling pathway, which further inhibited cell viability, invasion, migration, tumour growth and promoted GBM cell apoptosis and autophagy." (PMID 32000296, 2020). "These 3 tumours increased considerably HMGA2 mRNA levels, 3.5-, 76- and 57-fold after 7–10 days of culture compared to T0." (PMID 32251338, 2020). "High expression of human high-mobility group A2 (HMGA2) is related to tumor progression, a poor prognosis, and a poor response to therapy for CRC." (PMID 32842685, 2020). "In conclusion, we identified that lupeol was a repressor of the tumor by regulating the expression of miR-212-3p, which targeted HMGA2, and miR-212-3p functioned as an oncogene in OS progression." (PMID 32883329, 2020). "Gain of chromosome 12q is a characteristic genomic alteration or landmark in most MAS, and HMGA2 gain/overexpression is significantly associated with MAS with SO and seems to be associated with tumor progression." (PMID 32351899, 2020). "Intriguingly, IGF2BP1, LIN28B, and HMGA2 form a self-promoting network antagonizing the tumor-suppressive actions of the let-7 miRNA family." (PMID 32545414, 2020).
tumor (continued). "The loss of SIRT6 in PDAC tumor models was associated with upregulation of LIN28B and consequently increased expression of the let-7 targets HMGA2, IGF2BP1, and IGF2BP3." (PMID 32545414, 2020). "HMGA2 expression in normal myometrial cells induces its transformation toward putative tumour-initiating leiomyoma cells." (PMID 32251338, 2020). "More recently, nuclear DR5 was discovered to result in increased levels of malignancy-promoting factors HMGA2 and Lin28B and enhanced tumor cell proliferation in vitro and in vivo." (PMID 32784606, 2020). "Numerous studies demonstrated that HMGA2 can drive inflammatory pathways, facilitating tumor progression and refractory disease." (PMID 32842685, 2020). "Let‐7 was negatively correlated with aspect ratio, RNA levels of pluripotency marker HMGA2, proliferation, invasion, spheroid number and size, and in vivo tumor growth, formation, and burden." (PMID 32652647, 2020). "It was also shown that high expression of HMGA2 is related to tumor progression, a poor prognosis, and a poor response to therapy." (PMID 32842685, 2020). "The majority were HMGA2 fusions with partner genes and subsequently formation of chimeric transcripts with gain of HMGA2 gene function and tumor formation." (PMID 31900140, 2020). "Other authors have reported that miR-98 reduces tumour aggressiveness through the inhibition of HMGA2 expression." (PMID 31979076, 2020). "Following translocation, the HMGA2 3′UTR was frequently found to be bound to the 3′ end of tumour suppressor genes, such as RAD51L1 and FHIT, thus further promoting tumorigenesis." (PMID 31979076, 2020). "Nine weeks after injection, the tumor volume was 80.7 ± 89.9 mm3 for HMGA2-expressing cells but 396.3 ± 359.4 mm3 for control cells (P = 0.12)." (PMID 32489328, 2020). "As such, at high levels of expression, HMGA2 is a critical determinant of tumor response to chemotherapy and tumor cell survival and invasiveness." (PMID 32365712, 2020). "On the contrary, HMGA2 overexpression promoted cell viability, invasion, migration, tumour growth while inhibiting GBM cell apoptosis and autophagy." (PMID 32000296, 2020). "Knockdown of HMGA2, or suppressing HMGA2 expression with histone deacetylase inhibitors, inhibited E/M plasticity and stemness in vitro and markedly reduced tumor growth and metastasis in vivo." (PMID 33297508, 2020). "The expression of HMGA2, a major factor for tumor invasiveness and metastasis, was also evidently increased in KMS lung tumors." (PMID 32081882, 2020). "The let-7 family members, widely viewed as tumor suppressor microRNAs (targeting multiple oncogenes such as HMGA2, c-Myc, RAS, and cyclin D1), are frequently reduced in cancer, which correlates with increased tumorigenicity and poor prognosis." (PMID 32560271, 2020). "It was also confirmed that lupeol exerted a tumor-suppressor role in OS through the miR-212-3p/HMGA2 axis." (PMID 32883329, 2020). "One possible explanation is that aberrant expression of MALAT1 acts as a ceRNA for miR-490, and high-expression MALAT1 inhibits miR490 and then increased expression of HMGA2 (the target of miR490), finally accelerating to tumor progression." (PMID 32426332, 2020). "Other evidence of the role of HMGA1 and HMGA2 in maintaining a stem cell state has been found in different types of tumor cells, among which we will only provide a few examples." (PMID 31963852, 2020). "Comparison of the staining intensity between KLK6 and HMGA2 demonstrated a Spearman correlation of 0.70 (p < 0.001) with significant positivity in tumor (0.91, p < 0.01) and adjacent (0.81, p = 0.003) tissues." (PMID 31692974, 2019). "Treatment with miR‐9 mimics inhibited tumor growth, potentially via down‐regulating HMGA2 expression." (PMID 31408273, 2019). "We found that HMGA2 knockdown inhibited many tumour signalling pathways, such as the EGFR, TGF-β, cell cycle, and PI3K-AKT signalling pathways." (PMID 31053152, 2019).
tumor (continued). "Clinically, this role of HMGA2 translated into enhanced olaparib resistance in tumor cells and highlights the importance of HMGA2 as a novel predictive biomarker for the response to PARP inhibitors in tumor cells." (PMID 30289618, 2019). "The effects of HMGA2 on tumor cell behavior, such as proliferation, invasion, and metastasis, have been reported in many types of cancer." (PMID 31684108, 2019). "Our results suggest that HMGA2 is a predictor for the tumor response to PARP inhibitors and is an attractive therapeutic target for combination therapies using DNA damaging drugs or radiation and PARP inhibitors." (PMID 30289618, 2019). "We therefore suggest that other/additional mechanisms and/or genes are involved in the pathway leading to overexpression of HMGA2 in this tumour type." (PMID 31217897, 2019). "A TGI of 100% or more indicates tumor regression, and our analysis confirmed that overall regression was only observed in HMGA2-positive PDX models." (PMID 31067275, 2019). "Increasing studies showed that the expression of let-7 in the tumor was downregulated and can inhibit the gene expression of HMGA2 and MYC at the transcriptional level." (PMID 31196036, 2019). "MiR‐204 expression was strongly downregulated while HMGA2 mRNA expression was increased in CRC tissue samples, compared that in adjacent non‐tumor tissues, indicating that the expression levels of miR‐204 and HMGA2 were indeed dysregulated in CRC." (PMID 30938104, 2019). "In vivo, transfection with miR‐9 mimics down‐regulated the expression of HMGA2, thus leading to a dramatic reduction in tumor growth in a mouse xenograft model." (PMID 31408273, 2019). "In the present study, we have identified the chromatin‐binding protein HMGA2 as a new endogenous modulator of PARP1 activity causing accelerated and enhanced PARylation upon DNA damage in human tumor cells." (PMID 30289618, 2019). "VEGFA and HMGA2 have both been reported to be dysregulated and promoted tumor progression in various cancers." (PMID 30755600, 2019). "In TNBC, miR-150 was found to be down-regulated in tumor tissues, and to regulate HMGA2, leading to suppression of migration in vitro." (PMID 31906022, 2019). "Consistent with the reduced olaparib‐induced PARP1 trapping in the presence of HMGA2, silencing HMGA2 was required to significantly reduce cell viability in our tumor cell models upon olaparib treatment in MMS exposed cells." (PMID 30289618, 2019). "Our results reveal that HMGA1 and HMGA2 mRNA and protein are overexpressed in ECC, but only HMGA1 expression is associated with increased histological grade and tumor size." (PMID 31096664, 2019). "In the analyzed subset of clinical samples, a positive correlation between KLK6 and HMGA2 was found in the tumor samples and adjacent tissues (Spearman correlation coefficient is 0.91, p < 0.01, and 0.81, p = 0.03, respectively)." (PMID 31692974, 2019). "Strikingly, an overall regression of tumor volumes over a period of 39 days was only observed in HMGA2-positive PDX models." (PMID 31067275, 2019). "The results demonstrated that miR‐9 was highly expressed in tumor tissues transfected with miR‐9 mimics, whereas the mRNA and protein levels of HMGA2 were also reduced by qRT‐PCR, immunohistochemistry and western blot." (PMID 31408273, 2019). "The accumulated evidence suggests that high expression of HMGA2 is related to tumor progression, poor prognosis, and a poor response to therapy." (PMID 31684108, 2019). "HMGA2 is considered a tumour stem cell marker that is highly expressed in many malignant tumours but not in normal tissues." (PMID 31053152, 2019). "Recent studies have reported that overexpression of IGF1R and HMGA2 enhances tumor growth and migration in prostate cancer and colorectal cancer, respectively." (PMID 29507664, 2018).
tumor (continued). "We found a dramatic upregulation of the canonical NOTCH1 target gene HEYL and a concurrent downregulation of HMGA1 and HMGA2 in fibroblasts co-cultured with JAG1-expressing tumour cells, particularly A549 and Hep3B cells." (PMID 29743479, 2018). "HMGA2 has emerged as a candidate tumour biomarker because it is overexpressed in many cancer patients and is undetectable in adults under normal physiological conditions." (PMID 29391048, 2018). "Our results collectively suggest that miR-219-5p inhibits tumor growth and metastasis by targeting HMGA2." (PMID 30474570, 2018). "The exceptional re-expression of HMGA2 by chromosomalrearrangements at chr12q13-15 in neoplasia of mice or humans, such as HCC and lungcancer, is involved in the let-7 deletion or loss of let-7-binding sites (28, –30)." (PMID 29742265, 2018). "In summary, the results in our study all confirm that miR‐541 functions as a tumor suppressor in SCLC by targeting HMGA2." (PMID 29659195, 2018). "In particular, tumours were the smallest in the group co-transfected with sh-HMGA2 with agomir-302a-5p/367-3p." (PMID 29391048, 2018). "miRNAs regulating the activity of HMGA2 are considered major molecular mediators in tumour metastasis." (PMID 29391048, 2018). "Accumulating studies have demonstrated that high-mobility group A2 (HMGA2), an oncofetal protein, plays a role in tumor development and progression." (PMID 30474570, 2018). "The oncogenic properties of HMGA2 have been shown to influence a variety of biological processes, including tumor growth, DNA damage response, and EMT." (PMID 29507664, 2018). "In tumours from KP172CT;Hmga2CK/+ mice, Hmga1 and Hmga2 were expressed in primary tumour areas as well as in metastases in liver and lung." (PMID 30228296, 2018). "Then, orthotopic tumor transplantation was further applied to confirm the oncogenic effect of HMGA2." (PMID 29733521, 2018). "HMGA2 is widely considered a driving factor of EMT in tumours; additionally, it is known that miRNA-mediated regulation of target genes can lead to reversal of EMT." (PMID 29391048, 2018). "In PDAC from KPHetCT;Hmga2+/+ mice the expression of Hmga1 and Hmga2 generally overlapped, with Hmga1 also being highly expressed in advanced primary tumours as well as in metastases." (PMID 30228296, 2018). "Recent studies have revealed that the overexpression of HMGA2 correlates with higher lymph node metastasis rates, poor tumor differentiation, and unfavorable prognosis, implying that HMGA2 has prognostic value in cancer." (PMID 29416690, 2018). "Briefly, tumor growth curves showed that 5-FU inhibited tumor growth in both the HMGA2-overexpressing and vector groups." (PMID 29515783, 2018). "The expression of both HMGA1 and HMGA2 has been shown to correlate with advanced tumour stages and metastasis in PDAC patients." (PMID 30228296, 2018). "After systemic administration of the aptamer-miRNA chimera in A549 tumor-bearing immunodeficient mice, there was down-regulation of let-7g target HMGA2 as well as inhibition of tumor growth." (PMID 30340426, 2018). "The mean tumor size and weight in the HMGA2-transfected group were significantly higher than those in the control group after 5-FU treatment." (PMID 29515783, 2018). "The luminescence quantification results showed that the HMGA2 overexpression group had a remarkably larger tumor size than the control groups." (PMID 29733521, 2018). "We performed transwell and orthotopic tumor implantation assays to assess the effect of HMGA2 on the GBM migration and invasion process." (PMID 29733521, 2018). "In particular, two different papers published in 2007 described the presence of chromosomal rearrangements at the 3′UTR of the HMGA2 locus, resulting in the escape of HMGA2 from let-7 regulation and the consequent promotion of tumor formation." (PMID 29419779, 2018). "To further demonstrate that the tumour cells that formed the VM were overexpressing HMGA2, we performed immunofluorescent staining in 3D-cultured cells." (PMID 28533522, 2017).